MTOR (mechanistic target of rapamycin kinase)
Diseases named in the same sentence as MTOR in open-access papers (continued):
Sharing a sentence is not in itself a finding about the gene and the disease.
breast cancer (continued). "The results suggest that plumbagin is unlikely to block HIF-1α signaling and its target genes by interrupting the PI3K/Akt/mTOR signaling pathway in MCF-7 breast cancer cells." (PMID 36080483, 2022). "The combination of mTOR inhibition with ET has been extensively studied in the metastatic breast cancer setting." (PMID 36046843, 2022). "A previous study found that luteolin induced apoptosis by blocking the PI3K/AKT/mTOR pathway in tamoxifen-resistant breast cancer cells." (PMID 35678671, 2022). "Alisol A, a triterpenoid in the Alismatis rhizome, promotes autophagy and inhibits PI3K/AKT/mTOR in breast cancer cells." (PMID 36139919, 2022). "Tubeimosides inhibit the activity of PI3K/Akt/mTOR signaling pathway, thus inhibiting the migration ability of breast cancer MDA-MB-231 cells." (PMID 36160391, 2022). "Diosgenin increases the phosphorylation level of JNK to inhibit the proliferation of the breast cancer cells with a high expression of human epidermal growth factor receptor and to promote cell apoptosis, possibly by inhibiting Akt and mTOR phosphorylation." (PMID 35698571, 2022). "The highly bone metastatic variant of the MDA-MB-231 breast cancer model, 1833, showed PI3K/mTOR activation, high levels of p27pT157 and p27pT198, and p27-dependent motility/invasion in vitro." (PMID 35372035, 2022). "The data indicated that lobaplatin, microwave hyperthermia and combination treatment induced breast cancer cell apoptosis via suppression of the PI3K/AKT/mTOR signaling pathway and activation of the JNK signaling pathway." (PMID 34282830, 2022). "Findings of the study revealed that Eupafolin led to inhibition of cell proliferation in E0771 breast cancer cell lines and caused G0/G1 phase arrest through the PI3K/Akt/mTOR signaling pathway." (PMID 35795855, 2022). "Here, we showed that ATRAP activates the AKT/mTOR signaling and acts as an oncogene to promotes breast cancer progression." (PMID 35414770, 2022). "This is of particular interest because mTOR signaling is known to be dysregulated in many human cancers, including breast cancer." (PMID 35712465, 2022). "In conclusion, we uncovered a USF1-ATRAP-PBX3-AKT/mTOR axis that functions in breast cancer tumor progression both in vitro and in vivo." (PMID 35414770, 2022). "The mTOR inhibitor INK-128 can restore the sensitivity of lapatinib-resistant HER2+ breast cancer cells to TKIs." (PMID 36010585, 2022). "Several chemical drugs such as rapalogs, derivatives of mTOR inhibitor rapamycin, have been approved for treating renal cell carcinoma, osteosarcoma, and breast cancers." (PMID 34431239, 2022). "Quercetin suppresses the proteasome function in breast cancer cells, resulting in blocking MTOR activity by a decrease in the MTOR substrates EIF4EBP1/4E-BP1 and RPS6KB/p70S6 kinase phosphorylation, consequently triggering autophagy." (PMID 36497321, 2022). "Other prevalent mTOR upstream mutations are found in AKT, with impairment or mutation of AKT and PTEN loss identified in breast cancer." (PMID 36428613, 2022). "This expands earlier reports that polyphosphates recruit Akt and mTOR in human endothelial cells and breast cancer cells." (PMID 36405694, 2022). "As mentioned, the PTEN/PI3K/AKT/mTOR pathway is often hyperactivated in TNBC and has been associated with chemoresistance in breast cancer." (PMID 36060249, 2022). "Quercetin inhibited glycolysis via activating the Akt-mTOR pathway, resulting in the activation of autophagy, hence inhibiting the migration of breast cancer cells." (PMID 36233051, 2022). "In summary, we found that MED16 plays an important role in breast cancer progression and treatment, and that its mechanism mainly depends on the activation of mTOR." (PMID 36294896, 2022). "Following the positive results of the BOLERO-2 trial, everolimus was the first mTOR inhibitor to be approved in the treatment of breast cancer, when used in combination with exemestane." (PMID 36046843, 2022).
breast cancer (continued). "Human epidermal growth factor receptor 2 (HER-2) and estrogen receptor (ER)-α are upstream molecules of the PI3K/AKT/mTOR signaling pathway, which is very important for diagnosing and treating breast malignant tumors." (PMID 36171591, 2022). "For example, increased activity of the PI3K/Akt/mTOR pathway observed in breast cancer can lead to an increased level of HIF-1α." (PMID 36139678, 2022). "For example, one of the top pathways, Reactome’s VESICLE MEDIATED TRANSPORT (FDR-adjusted p value < 6E−4), involves ER-to-Golgi transport machinery that co-regulates with the mTOR proteins in proliferation and growth of breast cancer cells." (PMID 36168036, 2022). "Pilaralisib, another pan-PI3K inhibitor, as well as the dual PI3K/mTOR inhibitor voxtalisib were each tested in combination with letrozole in phase I/II trial of AI-refractory breast cancer." (PMID 36046843, 2022). "AZD8055 is a second-generation mTOR inhibitor that inhibits protein synthesis in HCs, inhibits malignant mammary tumor cell proliferation and reduces tamoxifen resistance." (PMID 36539659, 2022). "In summary, targeting the PI3K/Akt/mTOR pathway to subvert resistance to ET in breast cancer is now proven to be of clinical benefit with everolimus and alpelisib already used routinely in clinical practice." (PMID 36046843, 2022). "Overexpression of OGN significantly inhibits cell proliferation and migration/invasion and reverses EMT phenotypes in breast cancer cells through its effects on the PI3K/AKT/mTOR pathway." (PMID 36421687, 2022). "Everolimus is an orally administered inhibitor of the mammalian target of rapamycin (mTOR) and used in breast cancer, some neuroendocrine tumors, and renal cell carcinoma (RCC) as an antineoplastic agent." (PMID 35307634, 2022). "The hotspot mutation H1047R in oncogenic PIK3CA was often detected in breast cancer, which enhances the enzymatic activity of PI3K and activates the AKT/mTOR signaling pathway." (PMID 35966080, 2022). "In breast cancer, mTOR expression correlated with a worse prognosis, and p-mTOR was more commonly detected in triple-negative breast cancers." (PMID 35883111, 2022). "Deglycosylated EpCAM was found to be a functional marker that was required for AKT/mTOR mediated autophagy regulation in breast cancer cells." (PMID 34983878, 2022). "Strikingly, we found that chemical inhibition of mTOR drives exon skipping in both MEFs and human breast cancer cell lines." (PMID 36293270, 2022). "Everolimus is an mTOR inhibitor used in combination with the aromatase inhibitor exemestane for postmenopausal women with HR-positive advanced breast cancer." (PMID 35089453, 2022). "In this regard, flavonoids were targeted in chemoresistant breast cancer focusing on mTOR signaling that resulted in effective therapeutic efficacy." (PMID 35795855, 2022). "The PI3K/Akt/mTOR pathway also participates in breast cancer proliferation, and the survival and activation of this pathway mediate anti-estrogen resistance." (PMID 35053443, 2022). "The effect of combination of a polyamine biosynthetic inhibitor and mTOR pathway inhibitor in the breast cancer cell was also assessed." (PMID 36135836, 2022). "In ER+ breast cancer cells harboring PIK3CA and PTEN mutations, treatment with a PI3K/mTOR inhibitor resulted in increased RTK-mediated signaling and upregulation of EGFR/ERK/p-BadS112." (PMID 35053443, 2022). "The efficiency of Sapanisertib, a third generation ATP competitive inhibitor of mTOR, has been demonstrated in vitro and in vivo in breast carcinoma, bladder carcinoma, and renal cell carcinoma." (PMID 35326726, 2022). "Decorin has previously been shown to activate autophagy in endothelial cells, through VEGFR2/AMPKα activation and mTOR inhibition, and in breast carcinoma cells and activates autophagy flux in glioma cells and intestinal cells." (PMID 35787306, 2022).
breast cancer (continued). "In one study including canine mammary carcinomas, p-mTOR labelling was found in 78% of the cases (n = 45) and in another study on canine prostatic carcinomas p-mTOR occurred at higher levels (more than 75%)." (PMID 35883491, 2022). "Astaxanthin reduces the growth of breast cancer cells by inhibiting the PI3K/Akt/mTOR pathway, followed by subsequently blocking translation of the MYC protein, which is essential in oncogenesis." (PMID 34579037, 2021). "In recent years, numerous papers dedicated to the expression of genes and proteins related to the PI3K/Akt/mTOR pathway in breast cancer have been created." (PMID 33669698, 2021). "Several preclinical studies have indicated that PI3K/AKT/mTOR inhibitors have an important effect on reversing the chemoresistance of breast cancer." (PMID 33790792, 2021). "The quercetin administration (0–200 μM) suppresses PI3K/Akt/mTOR axis in induce cell cycle arrest in G1 phase in breast cancer cells." (PMID 34769099, 2021). "Others have reported that gigantol inhibits the proliferation of breast cancer cells by downregulation of the phosphoinositide 3-kinase/protein kinase B/mammalian target of rapamycin (PI3K/Akt/mTOR) signaling pathway." (PMID 35723385, 2021). "An inhibitor of the AKT/mTOR pathway, LY-294002, reversed the proliferation and invasion of breast cancer induced by GABARAP knockdown." (PMID 33591943, 2021). "Dysregulation of the PI3K/AKT/mTOR pathway are very common in many types of human cancers, including breast cancer." (PMID 33413418, 2021). "mTOR is activated in breast cancer through HER-2 overexpression, PI3K pathway alteration, and mTOR mutation." (PMID 34552932, 2021). "In this review, our perspective is that PI3K/AKT/mTOR pathway activation is related to conventional therapy resistance in breast cancer, including endocrine therapy, HER2-targeted therapy, CDK4/6 and PARP inhibitors, chemotherapy and immunotherapy." (PMID 33790792, 2021). "Currently, the mTOR inhibitor Everolimus is used in combination with ET with significant benefit over ET alone in ERα+/Her2− advanced breast cancer patients who have failed prior ET." (PMID 34298826, 2021). "MEDAG promotes breast cancer cell proliferation, pro-metastasis, and EMT through the AKT/AMPK/mTOR pathway and reduces epirubicin sensitivity in breast cancer cells via AKT/AMPK." (PMID 33462219, 2021). "Metformin also suppressed dipeptidyl peptidase-4 (DPP-4) inhibitor-induced EMT via the suppression of mechanistic target of rapamycin (mTOR) signaling in breast cancer." (PMID 34399790, 2021). "For instance, lncRNA UASR1 promotes cell growth and migration of breast cancer cells by regulating AKT/mTOR pathway." (PMID 33672592, 2021). "According to the published data, the PI3K/AKT/mTOR pathway is activated in approximately 70% of ovarian or breast cancers." (PMID 33572326, 2021). "Previous studies performed in human breast cancer cells revealed that trisubstituted imidazole drugs targeting the oncogenic PI3K/AKT/mTOR pathway can lead to apoptosis of breast cancer cells." (PMID 34931134, 2021). "Previous studies have documented that three kinds of flavonoid isolated from T. kirilowii induced G2/M cell cycle arrest, apoptosis, and autophagy through the downregulation of PI3Kγ-mediated PI3K/AKT/mTOR signaling in human breast cancer cell lines." (PMID 34093198, 2021). "Inhibition of dipeptidyl peptidase (DPP)-4 stimulated CXCL12/CXCR4 expression and activated mTOR signaling, which further induced epithelial-mesenchymal transition of breast cancer cells and metastasis." (PMID 34234860, 2021). "Previously, it was found that miR-147 ectopic expression resulted in a decreased activation of the Akt/mammalian target of rapamycin (mTOR) in breast cancer cell lines." (PMID 34831256, 2021).
breast cancer (continued). "Other studies demonstrate that combining mTOR (mammalian target of rapamycin) inhibitor rapamycin with AKT inhibitors has a synergistic effect on breast cancer, but these combinations have yet to make their way into the clinic." (PMID 34461089, 2021). "Hyperactivation of PI3K/AKT/mTOR pathway drives tumorigenesis of ER+ breast cancer and resistance to endocrine therapy." (PMID 33861751, 2021). "The combined use of trastuzumab and mTOR inhibitors has been shown to be more effective to treat HER2-positive breast cancer than single agents." (PMID 34204960, 2021). "This review focuses on the clinical efficacy and toxicity of mTOR inhibitors in HER2-positive breast cancer, but these have been assessed in many other cancers." (PMID 34208071, 2021). "The mTOR inhibitor rapamycin targets mTOR and is highly effective in treating breast cancer, cervical cancer, and HNSCC." (PMID 33660438, 2021). "AKT/mTOR pathway plays crucial roles in multiple biological processes, including cell proliferation, migration, cell cycle progression and apoptosis in breast cancers, NSCLC, colorectal cancers and other human cancers." (PMID 33269380, 2021). "In breast cancer, Piezo1 initiates Akt/mTOR signaling, a pathway responsible for regulating cell motility and survival." (PMID 34831037, 2021). "Numerous studies showed that the PI3K/AKT/mTOR signaling pathway activates upstream receptors (EGFR and PDGF) and is mutated in a variety of cancers, including breast cancer, gastric cancer, and NSCLC." (PMID 34580719, 2021). "Inhibitors of the PI3K/AKT/mTOR pathway combined with existing treatment methods can act to overcome drug resistance in different subtypes of breast cancer." (PMID 33790792, 2021). "The authors documented that human breast cancer tissue specimens exhibited a positive correlation between acetyl-MnSODK68 levels and phospho-Ser2481 mTOR levels." (PMID 33435147, 2021). "The biologic implications and therapeutic potentials of the observed mTOR signaling dysregulation in mammary epithelial cells in breast cancer microenvironment should be further explored." (PMID 33446797, 2021). "Overall, this study strongly supports the use of combining CDK4/6 inhibitors and antiestrogens with mTOR inhibitors to delay the onset of ER+ breast cancer resistance." (PMID 34830174, 2021). "Based on these promising findings, a concerted effort was undertaken to examine the therapeutic efficacy of mTOR inhibitors in various clinical trials, in both ER+ breast cancer as well as TNBC." (PMID 34540690, 2021). "For example, Bhlhe40 facilitates PI3K/Akt/mTOR activation and triggers tumor progression in breast cancer, whereas it represses STAT1 expression and activates tumor suppression in clear cell carcinoma." (PMID 33987177, 2021). "What’s more, intrinsic resistance is inevitable besides acquired resistance since PI3K/AKT/mTOR pathway is basally activated in multiple solid tumors, including breast cancer." (PMID 33790792, 2021). "In this review, we summarize the critical role of the PI3K/AKT/mTOR pathway in drug resistance, the development of PI3K/AKT/mTOR inhibitors, and strategies to overcome acquired resistance to standard therapies in breast cancer." (PMID 33790792, 2021). "Aberrations in phosphatidylinositol 3-kinase (PI3K)/protein kinase B (AKT)/mammalian target of rapamycin (mTOR) signalling pathways have been investigated in a metastatic breast cancer setting." (PMID 33923563, 2021). "Levobupivacaine represses cell survival by inhibiting the Akt/mTOR signaling in breast cancer cells." (PMID 34177591, 2021). "Quercetin can inhibit glycolysis by autophagy mediated by Akt-mTOR pathway, thereby inhibiting breast cancer metastasis." (PMID 34857023, 2021). "Our study ascribes separate roles for MeJA and MeJA‐derived compounds from Arabidopsis impacting mTOR in the breast cancer cell cycle." (PMID 33124043, 2021).
breast cancer (continued). "The Gene Set Enrichment Analysis (GSEA) associates the high tumor-associated neutrophil level to PI3K-AKT-mTOR pathway, which aligns with the previous finding of the group showing that mTOR signaling stimulates MDSC accumulation in the mammary tumor." (PMID 34026830, 2021). "The combination of everolimus (mTOR inhibitor) and olaparib (PARPi) has been tested in BRCA2-mutated breast cancer patient-derived xenografts (PDX) with promising results." (PMID 34572083, 2021). "The mTOR inhibitor everolimus has been previously used to treat breast cancers, but toxicity is a major issue with this drug and many patients stop treatment due to this issue." (PMID 34069042, 2021). "Phosphorylation and activation of AMPK have previously been demonstrated to reduce growth in breast cancer cells, primarily by inhibiting the mechanistic target of rapamycin (mTOR)-signaling pathway." (PMID 33946704, 2021). "Typical mutational and epigenetic changes in individual genes in the PI3K/AKT/mTOR pathway are characteristic of specific breast cancer subtypes." (PMID 34202777, 2021). "The phosphoinositide 3-kinase (PI3K)/AKT/mTOR pathway is the most important oncogenic pathway altered in breast cancer." (PMID 34202777, 2021). "Moreover, the highly expressed miR-100 maintains the phenotype of tumor-associated macrophages by targeting mTOR to promote tumor metastasis in mice, while intratumoral injection with an miR-100 inhibitor and combined cisplatin therapy showed better benefits for breast cancer therapy." (PMID 33915898, 2021). "Deregulation of the signaling pathway PI3K/Akt/mTOR has been demonstrated in several types of cancer, such as breast cancer and colorectal cancer." (PMID 33922320, 2021). "The present study used the stable COL17-overexpressing MCF7 and MDA-MB-231 cells to reveal an anti-proliferative effect of COL17 on breast cancer cell through mTOR deactivation." (PMID 34293053, 2021). "exon 9–10) PIK3R1, PTEN, AKT1, mTOR, was obtained using the real-time PCR technique in 54 breast cancer patients." (PMID 33669698, 2021). "Metformin-mediated autophagy via the activation of AMPK/mTOR pathways were found in multiple myeloma and breast cancer, and also in other cell types and animal models." (PMID 33652909, 2021). "No clinical studies have assessed the immunoregulatory effects of mTOR inhibitors in breast cancer patients so far." (PMID 34315439, 2021). "Of note, a significant portion of HR+ breast cancers shows dysregulation of the phosphoinositide 3 kinase (PI3K)/AKT/mammalian target of rapamycin (mTOR) signaling, which is also the main contributor to ET resistance." (PMID 34001143, 2021). "Another study showed the efficacy of the mTOR inhibitor everolimus in postmenopausal hormone receptor-positive advanced breast cancer." (PMID 33482765, 2021). "The AKT/mTOR pathway is among the most frequently dysregulated pathways in patients with breast cancer." (PMID 34201030, 2021). "Quercetin suppressed breast cancer progression by decreasing AKT/mTOR pathway, inducing autophagy, in vitro and in vivo, and inhibited AKT-mediated activation of mTOR and its effectors in hepatocellular carcinoma, prostate, and breast cancer cells." (PMID 33918290, 2021). "The association concerning the presence of mutations and changes in the expression of genes within the PI3K/Akt/mTOR pathway, as well as their impact on breast cancer prognosis, have been evaluated by many studies." (PMID 33669698, 2021). "mTOR activation is frequently reported in many human cancers, including lung, pancreatic, gastric, and breast cancers." (PMID 34869595, 2021). "The PI3K/AKT/mTOR pathway is frequently deregulated in breast cancer by different mechanisms, leading to increased PI3K activity and/or loss of PI3K inhibitory functions as well as mutation in tumor suppressor genes like INPP4B and PTEN phosphatases." (PMID 34298731, 2021).